AGR2 (anterior gradient 2, protein disulphide isomerase family member)
Diseases named in the same sentence as AGR2 in open-access papers (continued):
Sharing a sentence is not in itself a finding about the gene and the disease.
breast tumors (17 papers, 2003 to 2025). "Because both AGR2 and H6PD have been associated with breast tumor promoting effects, AGR2 was studied in more detail." (PMID 40281598, 2025). "AGR2 is another classically estrogen-responsive gene that is expressed in both cell lines and ER-positive breast tumours and that has been associated with a poor response to hormonal therapy." (PMID 17555561, 2007). "In the survival analysis of HER2 subgroup, it was found that in HER2 positive breast tumors, AGR2 expression was significantly increased at both mRNA and protein levels." (PMID 37197416, 2023). "Immunohistochemical analysis of human breast tumors (n = 44) revealed that there was a significant correlation between ERα positive and AGR2 expression." (PMID 37197416, 2023). "Due to the significance of molecular subtypes of BRCA, we also explored the expression pattern and prognostic impact of AGR2 in primary breast tumors." (PMID 36405393, 2022). "In this study, we confirmed that the expression and prognostic value of AGR2 were correlated with the subtypes of primary breast tumors." (PMID 36405393, 2022). "AGR2 is a protein disulfide isomerase and it is expressed almost exclusively in luminal breast tumours, where it is positively regulated by the oestrogen receptor." (PMID 34771489, 2021). "The KEGG NF-kB signaling pathway is downregulated in breast tumors with high AGR2 expression compared to those with low AGR2 expression within the METABRIC microarray dataset." (PMID 29796176, 2018). "Relative hazard of disease-specific death by AGR2 expression suggested z-score values of ± 1.5 as cut-point values to define AGR2 prognostic groups as high and low AGR2 expression breast tumor groups." (PMID 29796176, 2018). "The presence of AGR2 in primary breast tumors is correlated with poor survival, and elevated expression of AGR2 is related to treatment failure with tamoxifen." (PMID 23236365, 2012). "Furthermore, breast tumors that overexpress AGR2 exhibit downregulation of KEGG pathways epitomized by the inflammatory response, including Pathogenic Escherichia Coli infection, HTLV-1 infection, and TNF pathway." (PMID 29796176, 2018). "mRNA expression fold changes in DEGs of breast tumors with high AGR2 compared to those with low AGR2 were consistent with prior findings highlighting the roles of intracellular and extracellular AGR2 in tumorigenesis pathways mediated by estrogen signaling and Insulin Growth Factor 1 (IGF-1)." (PMID 29796176, 2018). "AGR2 expression was shown to be significantly increased in HER2 positive breast tumors." (PMID 28686225, 2017). "Therefore, blocking AGR2 directly may be an option for patients with HER2 positive breast tumors." (PMID 37197416, 2023). "Indeed, the downregulation of the “Estrogen-mediated S phase entry” pathway in breast tumors with high AGR2 mRNA expression—suggested by IPA analyses in both the METABRIC and TCGA datasets—may represent breast tumors that overexpress AGR2 to become resistant to estrogen therapy." (PMID 29796176, 2018). "A previous study enrolled 107 primary breast tumors of patients who had developed distant metastasis and classified all patients into two groups according to the site of relapse (bone vs. non-bone), finding that AGR2 was highly expressed in the samples with relapse to bone." (PMID 36405393, 2022).
colitis (15 papers, 2012 to 2024). Inflammation of the colon. "Agr2 knockout mice show loss of intestinal mucus, increased susceptibility to dextran sodium sulfate–induced colitis, and develop spontaneous ileitis and colitis accompanied by markers of increased ER stress." (PMID 34237462, 2021). "The protein disulfide isomerase AGR2 is highly expressed in secretory cells, and mice deficient in AGR2 develop terminal ileitis and colitis displaying Paneth cell hypertrophy and a loss of mucin-filled goblet cells along with UPR activation (Grp78 increase)." (PMID 31867005, 2019). "Deficiency of AGR2, an ER-resided disulfide isomerase, also disrupted intestinal tissue homeostasis and caused development of spontaneous ileitis and colitis in mice." (PMID 30701081, 2019). "Loss of TFF3, AGR2 was linked to impaired mucus and increased susceptibility to dextran sodium sulfate-induced colitis., GC Piezo1-/- mice exhibited decreased expression of Mucin2, TFF3, AGR2, and thinner mucus layer, which was consistent with the decreased GC numbers." (PMID 36425784, 2022). "Similarly, Agr2-deficient mice were highly susceptible to DSS-induced colitis due to abnormalities in MUC2 synthesis." (PMID 22514630, 2012). "ERdj5 knockout mice develop altered ER proteostasis in salivary glands, whereas AGR2/PDIA17 knockout mice are viable, but show decreased levels of mucin, an essential component of the protective mucus in the intestine, resulting on severe colitis." (PMID 26361352, 2015). "This role was found to protect mice from colitis but was solely an intracellular function of AGR2." (PMID 39727484, 2024). "Studies on mice lacking AGR2 revealed their heightened susceptibility to colitis, confirming the critical role of AGR2 in protecting against disease." (PMID 38528032, 2024). "Furthermore, consistent with the human IBD data,22 chemical-induced colitis enhanced Agr2 expression in mice specifically in the epithelial cell compartment." (PMID 36384110, 2022). "That is to say, GQDs and GOQDs can directly adhere on and cover the active site of AGR2 protein, which may inhibit the normally physiological binding of AGR2 active site to MUC2 (a direct involvement of AGR2 in mucin processing), finally heightening susceptibility to colitis." (PMID 38528032, 2024). "Mice lacking Muc2, Agr2 or having mutations in Muc2 that interfere with initial mucin folding and assembly develop spontaneous colitis or display rectal prolapse." (PMID 36245281, 2023). "Furthermore, mice lacking Agr2 were susceptible to colitis, suggesting a role in the protection from diseases such as inflammatory bowel disease." (PMID 22514630, 2012).
non-small cell lung carcinoma (12 papers, 2015 to 2025). A group of at least three distinct histological types of lung cancer, including non-small cell squamous cell carcinoma, adenocarcinoma, and large cell carcinoma. "ADAMTS6 has been linked to non-small cell lung cancer (NSCLC) through regulation of anterior gradient 2 (AGR2), an endoplasmic reticulum protein family member." (PMID 36339722, 2022). "miR-342-3p targets AGR2 and down-regulation of miR-342-3p is associated with over-expression of AGR2 in non-small cell lung cancer." (PMID 30665445, 2019). "Other studies have shown that ADAMTS6 may be associated with the occurrence of NSCLC (non-small-cell lung cancer) by affecting the regulation of AGR2 expression." (PMID 39940703, 2025). "Targeting AGR2 with miR-342-3p results in an inhibition of cell proliferation and migration in non-small-cell lung cancer (NSCLC)." (PMID 35909905, 2022). "Consistent with the report, AGR2 was preferentially expressed in non-small cell lung cancer (NSCLC) H460 and A549 cells." (PMID 30647455, 2019). "Using immunostaining, 63 out of 95 non-small cell lung cancer (NSCLC) samples (66%) were demonstrated to have an elevated AGR2 expression." (PMID 31247903, 2019). "Similarly, AGR2 promotes cell growth and migration through the Akt signaling pathway in non-small cell lung cancer; moreover, the phospho-Akt level is reduced after depletion of AGR2." (PMID 36899352, 2023). "In non-small cell lung cancer, AGR2 promotes cell growth and migration through the AKT signalling pathway whereby depletion of AGR2 reduces the phospho-AKT level." (PMID 33005802, 2020). "In our study, non-neoplastic bronchial epithelial cells as well as non-small cell lung cancer (NSCLC) cells express AGR2 protein." (PMID 26445321, 2015).
pancreatic ductal adenocarcinoma (11 papers, 2010 to 2025). An infiltrating adenocarcinoma that arises from the epithelial cells of the pancreas. "Zhang and colleagues designed an anti-AGR2 hexapeptide, NTAIYY, to target pancreatic ductal adenocarcinoma (PDAC) by competitively disrupting the AGR2-RNA polymerase II (RNAPII) complex." (PMID 40867591, 2025). "A study showed that LYPD3 stimulates proliferation, migration, invasion and drug resistance of pancreatic ductal adenocarcinoma (PDAC) cells by interacting with AGR2." (PMID 37924160, 2023). "The antibody-induced blocking of AGR2 in pancreatic ductal adenocarcinoma cell lines revealed a significantly reduced tumor growth and metastasis and led to tumor regression and improved survival." (PMID 31247903, 2019). "Monoclonal antibodies against AGR2 markedly reduce tumor growth and metastasis in pancreatic ductal adenocarcinoma, but this reduction has only been observed in preclinical mouse models." (PMID 30406031, 2018). "AGR2 is up-regulated in several solid tumors, including pancreatic ductal adenocarcinoma (PDAC)." (PMID 39727484, 2024). "In addition, the interaction between C4.4A with Anterior Gradient 2 (AGR2) stimulates pancreatic ductal adenocarcinoma cell aggressiveness and reduces sensitivity to chemotherapy drug gemcitabine." (PMID 32140067, 2020). "Subsequently, AGR2 downregulation was determined by immunohistochemical staining and correlated with vimentin expression and reduced expression of membranous E-cadherin in pancreatic precursor neoplastic lesions, as well as pancreatic ductal adenocarcinomas." (PMID 28810836, 2017). "Moreover, AGR2 expression is suppressed by SMAD4 that is a tumor suppressor of pancreatic ductal adenocarcinoma." (PMID 25367337, 2014).
colon cancer (9 papers, 2013 to 2024). "Tumour-suppressor genes (MLH1 and RUBCNL), protooncogene (AGR2), and genes reported to be linked with colon cancer (EPDR1, MLH1, AXIN2) were enriched in the signature." (PMID 31008109, 2019). "AGR2 has consistently emerged as a potential therapeutic target in colon cancer from various perspectives." (PMID 39062458, 2024). "Studies have indicated that reducing AGR2 expression in the serum can enhance drug efficacy, with initial observations made in colon cancer cases." (PMID 39062458, 2024). "for example showed that chemical crosslinking to human colon cancer cells, Hct8 cells, followed by immunoprecipitation of AGR2 and Western blotting identified both monomeric and dimeric AGR2 bands." (PMID 33005802, 2020). "A large number of samples in the ‘other cancer’ group were colon cancer samples and it is possible that AGR2 serum levels are increased at higher levels in PDAC compared to colon cancer." (PMID 24007603, 2013). "A study from 2006, also shows AGR2 mRNA levels to be downregulated in colon cancer; however firm conclusions cannot be made." (PMID 24007603, 2013).
head and neck squamous cell carcinoma (9 papers, 2015 to 2024). A squamous cell carcinoma that arises from any of the following anatomic sites: lip and oral cavity, nasal cavity, paranasal sinuses, pharynx, larynx, and salivary glands. "We sought to investigate the diagnostic and prognostic role of AGR2 on head and neck squamous cell carcinoma (HNSCC) with an emphasis on its correlation of cancer stemloid cells (CSC) and epithelial mesenchymal transition (EMT)." (PMID 25871396, 2015). "In ESCC, coexpression of MACC1 with Snail and AGR2, along with diminished KAI1, is associated with LNM in ESCC and head and neck squamous cell carcinoma (HNSCC)." (PMID 39399490, 2024). "Previous studies reported that AGR2 is involved in head and neck squamous cell carcinoma by regulating cell transformation and epithelial-mesenchymal transition (EMT) signaling pathways, and that it also promotes tumor growth in esophageal adenocarcinoma." (PMID 36327302, 2022). "In the head and neck squamous cell carcinoma (HNSCC) CAL27 cell line, AGR2 protein was highly expressed and shown to be overexpressed in the corresponding cancer stem cells (CSC)." (PMID 31247903, 2019).
inflammatory bowel disease (9 papers, 2012 to 2025). A spectrum of small and large bowel inflammatory diseases of unknown etiology. "In humans, AGR2 deficiency causes inflammatory bowel disease in part because AGR2 is required for production of the mucus proteins that form the colonic barrier that limits intestinal inflammation." (PMID 40867591, 2025). "AGR2 has been implicated in inflammatory bowel disease and cancer progression, and mechanically, promotes angiogenesis and increases the invasiveness of tumor cells." (PMID 38390317, 2024). "AGR2 deficiency induces mucus barrier dysfunction and infantile inflammatory bowel disease in humans." (PMID 37175601, 2023). "The role of AGR2 has been implicated in inflammatory bowel disease and cancer progression." (PMID 36327302, 2022). "More importantly, null AGR2 transgenic mice were shown to have defects in mucin production and a susceptibility to toxin-stimulated inflammatory bowel disease (IBD)." (PMID 31247903, 2019). "The role of AGR2 in maintaining intestinal homeostasis and pathogenesis of the inflammatory bowel disease was studied on the model of intestinal epithelial cells culture Caco-2." (PMID 37175601, 2023). "Recently, the dimerized AGR2 was demonstrated to act as a sensor of ER homeostasis and was shown to correlate with the severity of inflammatory bowel disease." (PMID 31247903, 2019). "The Mendelian deficiency of AGR2, termed “Enteropathy caused by AGR2 deficiency, Goblet cell Loss, and ER Stress” (EAGLES), results in a mucus barrier defect, the inability to mitigate ER stress, and causes infantile-onset inflammatory bowel disease." (PMID 34237462, 2021). "Furthermore, our data link the perturbation of AGR2 dimerization to inflammatory bowel disease in human in part through the unexpected intervention of AGR2 in the recruitment of inflammatory cells." (PMID 31040128, 2019). "Mouse AGR2 deletion increases intestinal inflammation and promotes the development of inflammatory bowel disease (IBD)." (PMID 31040128, 2019).
esophageal cancer (8 papers, 2012 to 2023). A primary or metastatic malignant neoplasm involving the esophagus. "Results suggested that the cytotoxicity sensitivity to cisplatin and 5-FU in esophageal cancer was associated with AGR2 expression." (PMID 36327302, 2022). "Results suggest that AGR2 gene was associated with therapy response of nCRT in esophageal cancer patients." (PMID 36327302, 2022). "We applied the siRNA approach to knockdown AGR2 expression in cell lines of esophageal cancer (CE146T/VGH, TE2, and CE48T/VGH) and then performed the MTT assay." (PMID 36327302, 2022). "In esophageal carcinoma, Prx4 has been identified to interact with AGR2, which is one of the proteins highly upregulated in this cancer." (PMID 36235049, 2022). "Being pro-oncogenic, the overexpression of AGR2 enhanced clonogenic growth and cancer cells survival, rather than inhibiting the growth of the cells in the premalignant Barrett's oesophagus and oesophageal cancers." (PMID 33005802, 2020). "Clinical studies have further shown that the AGR2 protein is overexpressed in a wide range of human cancers, including carcinomas of the esophagus, pancreas, breast, prostate, and lung." (PMID 23029506, 2012). "Clinical studies have shown that the AGR2 protein is overexpressed in a wide range of human cancers, including carcinomas of the esophagus, pancreas, breast, prostate, and lung, making the protein as a potential cancer biomarker." (PMID 23029506, 2012). "AGR2 is an ER chaperone known to promote tumor growth and migration in esophageal carcinoma." (PMID 36235049, 2022).
gastric cancer (8 papers, 2015 to 2022). A primary or metastatic malignant neoplasm involving the stomach. "Cancer-secreted AGR2 could activate stromal fibroblasts (cancer-associated stromal cells vs. normal tissue stromal cells) to promote fibroblast associated cancer invasion of gastric cancer cells." (PMID 27283903, 2016). "It is associated with metastasis and poor prognosis in gastric cancer, and overexpression of LINC01857 in HCC promotes cell proliferation by regulating AGR2 and upregulating the AKT and ERK pathways." (PMID 36168326, 2022). "In gastric cancer samples, AGR2 expression was examined in 436 cases, and the results indicated an elevated AGR2 expression in 204 of the 436 samples (47%)." (PMID 31247903, 2019). "AGR2 expression was up-regulated in a gastric cancer cell subline with high metastatic potential for invasion to lymph nodes." (PMID 27283903, 2016). "AGR2 expression was up-regulated in a gastric cancer cell subline with high metastatic potential for invasion of lymph nodes." (PMID 26894971, 2016). "In our study, we found that the overexpression of AGR2 was correlated with lymph node-positive status, which was also reported in gastric cancer." (PMID 25871396, 2015).